IL1B (interleukin 1 beta)
Diseases named in the same sentence as IL1B in open-access papers (continued):
Sharing a sentence is not in itself a finding about the gene and the disease.
Obesity (continued). "We detected increased mRNA levels of NLPR3 (P = 0.002), NLRP6 (P < 0.001) and its effectors IL1B (P = 0.002), IL8 (P = 0.047) and IL18 (P = 0.006) in VAT of patients with obesity and with obesity and T2D." (PMID 39707172, 2024). "In the future, we intend to focus on elucidating the mechanisms by which inflammatory factors IL‐1β and CXCL16 contribute to the development of obesity in HFD‐KI mice." (PMID 38145352, 2024). "Individuals with obesity exhibit markedly reduced immunological tolerance, leading to excessive production of inflammatory mediators such as IL-6, TNF-α, IL-1β, and IFN-γ, alongside a significant decrease in anti-inflammatory cytokines like IL-4 and IL-10." (PMID 38840158, 2024). "Our study revealed that a 6-month curcumin treatment significantly reduced IL-1β, IL-6, and TNF-α in type 2 diabetes patients with obesity." (PMID 39125322, 2024). "The increased expression of Il1β and Cd80 underscored the shift towards a pro-inflammatory macrophage profile in WAT during obesity." (PMID 39683572, 2024). "Here the authors show IL-1β regulates WAT remodelling by promoting adipogenesis and energy storage, which is blocked by chronic elevation of this cytokine (as in obesity)." (PMID 39261467, 2024). "Investigation of the inflammatory status of BAT documented an increase in immune responses in HFD-induced obesity conditions relative to some of the inflammatory markers tested here, such as TNF-α, IL-1β, and IL-6 cytokines." (PMID 38671836, 2024). "This is because circulating levels of pro‐inflammatory cytokines, such as interleukin (IL)‐1β and C‐reactive protein (CRP), are increased in individuals with obesity." (PMID 39107107, 2024). "Inflammation has been regarded as a critical mechanism of cognitive dysfunction in human and animal models of obesity, evidenced by the accumulation of proinflammatory cytokines (TNF-α, IL-1β, and IL-6)." (PMID 36334250, 2023). "Stress granules (G3BP1) were significantly induced by the HFD in both sexes; conversely, inflammatory (IL-1β) responses were observed only in the male liver and cochlea, consistent with phenotype HFD-induced obesity." (PMID 36810096, 2023). "In T2D and obesity, FFAs are also necessary for the activation of the NLRP3 and the production of IL-1b." (PMID 37241737, 2023). "For example, during the early stages of HFD-induced obesity, MMe macrophages increased adipose tissue inflammation by upregulating inflammatory markers such as TNF-α, IL-6, and IL-1β, as well as genes involved in lipid metabolism." (PMID 37153549, 2023). "Inflammatory pathways, including NF-κB signaling, are aggravated in adipose tissues affected by obesity, resulting in the elevated expression of subsequent cytokines such as TNFα, IL6, IL1β, and others." (PMID 37764703, 2023). "In conclusion, IL-1β, IL6, IL-10, and IP-10 levels are elevated in adolescents with severe obesity and these cytokines can serve as a tool for the diagnosis of MetS." (PMID 37336969, 2023). "IL-1β, TNF-α and IL-6 are inflammatory cytokines correlated with and involved in obesity-related inflammation and insulin resistance, respectively." (PMID 37796781, 2023). "MUFA can inhibit adipose (NLRP3) inflammasome-mediated IL-1β secretion, NLRP3 secretion, and insulin resistance, even in mice with diet-induced obesity." (PMID 37175603, 2023). "Our results agree with previous findings, where obesity-induced chronic low-grade inflammation generates an increase in MCP-1, IL-1β, and IL-6 as observed in the HD group at 6 and 13 months." (PMID 37139092, 2023). "In the mouse model of obesity-induced HCC, aged hepatic stellate cells produce a significant amount of SASP, including IL-1β and IL-1β-dependent IL-33." (PMID 38169837, 2023). "MCP-1 is stimulated by the presence of IL-1β, TNF-α, IL-8, IL-4, and IL-6, and thus further aids in the macrophage recruitment to adipose tissue seen in obesity." (PMID 37571308, 2023).
Obesity (continued). "During obesity, macrophages infiltrate and produce cytokines such as tumor necrosis factor-alpha (TNF-α), interleukin 1 beta (IL-1β), IL-18, IL-6, and interferon-gamma (IFN-γ)." (PMID 37214340, 2023). "Usually, pregnant women with obesity at pre-pregnancy or becoming obese have a lipotoxic placental environment leading to increased OS and elevated concentrations of TNF-α, IL-1, IL-1β, IL-3, IL-4 and IL-6, and IFN-γ." (PMID 37891973, 2023). "Animal models with diet-induced obesity have high levels of pro-inflammatory cytokines such as TNF-α, IL-1β, and IL-6 and activation of microglia and astrocytes in the hypothalamus." (PMID 37373230, 2023). "The aim of this study was to evaluate the effect of serum selenium on PPAR-γ and the selected proinflammatory cytokines (IL-1β, IL-6, TNF-α) in relation to depressive symptoms and obesity in middle-aged women." (PMID 37049434, 2023). "Obesity, diabetes mellitus, and metabolic syndrome are diseases mediated by proinflammatory cytokines such as TNF-α, IL-1β, and IL-6." (PMID 37685515, 2023). "After feeding high-fat and high-sucrose diets mixed with Hericium erinaceus mycelium (HEM) or EA for 18 weeks, lowering hippocampal messenger RNA (mRNA) expressions of TNF-α and IL-1β, HEM and EA limit the progression of obesity-induced neurodegeneration." (PMID 36675019, 2023). "Pregnant women with obesity and diabetes often have an increase in pro-inflammatory cytokines and adipokines, such as TNF-α, IL-6, IL-1β, leptin, and resistin, which are involved in the inflammatory response." (PMID 37515062, 2023). "In individuals with obesity, the production of pro-inflammatory adipokines (leptin, TNF-α, resistin, visfatin, IL-6, and IL-1β) is increased and that of anti-inflammatory cytokines (e.g., adiponectin) is decreased." (PMID 37364142, 2023). "Obesity results in the activation of the NLR family CARD-containing protein 4 inflammasome in macrophages to increase their infiltration and produce IL-1β." (PMID 36593475, 2023). "Inflammatory biomarkers including hs‐CRP, IL‐6, IL‐4, IL‐1B, IL‐10, and TNF‐α have also been shown to be connected with obesity, diabetes, and CVD." (PMID 36911829, 2023). "Diet-induced obesity increases the activation of inflammation in the mediobasal hypothalamus, resulting in the production of proinflammatory cytokines (TNF-α, IL-1β, and IL-6) and impairment in insulin and leptin signaling." (PMID 36677011, 2023). "Due to adipose tissue dysfunction in states of obesity, WAT predominantly expresses proinflammatory adipokines and cytokines, such as Il-1b, Il-6, Il-12, TNF-α or interferon gamma, which contribute to the conditions of chronic systemic inflammation in obesity." (PMID 37239098, 2023). "Nowadays, evidence is apparent that obesity-induced activation of inflammatory cytokines (e.g., NLRP3, IL-1β, IL-18) is a major culprit behind the adiposity-related metabolic complication." (PMID 37935689, 2023). "CGA has been shown to reduce oxidative damage, control the inflammatory response through inhibition of TNF-α, IL-6, and IL-1β, increase insulin sensitivity, and prevent CVD and obesity through lipid metabolism modulation." (PMID 35683374, 2022). "SAA is a nonspecific acute phase protein mainly produced by the cytokines IL-1β, IL-6, and TNF-α in liver cells, which increase in chronic inflammatory processes, as in diabetes and obesity." (PMID 35047039, 2022). "For example, in obesity-induced asthma, ILC3 can release IL-17 in reaction to macrophage-derived IL-1β." (PMID 35122179, 2022). "Specifically, we observed the levels of IL-1β, IL-6, IL-8, IL-12, IL-17, IL-21, IL-32, and TNF-α were significantly higher in the NAFLD group than in the simple obesity group (all P < 0.001)." (PMID 36530698, 2022). "In a transgenic mouse model of PDAC, obesity in mice induces steatosis and a fibroinflammatory TME in which IL-1B is released by adipocytes." (PMID 35740306, 2022).
Obesity (continued). "In addition, the different response of visceral versus subcutaneous AT suggests that not systemic calcium concentrations as determined in the serum of peripheral blood are most relevant for [Ca2+]ex-induced IL-1β release in obesity, but that local tissue concentrations could be the trigger." (PMID 35931812, 2022). "During obesity, macrophages in adipose tissue express high levels of NLRP3 and release inflammatory cytokines such as TNF-α and IL-1β." (PMID 35844498, 2022). "Increases in the levels of ILC3s are observed in adipose and lung tissues in obesity, and ILC3s can mediate the development of AHR in HFD-induced obese mice with NLRP3 and IL-1β." (PMID 36051916, 2022). "Endurance exercise intervention (ApoE WD EX) significantly alleviated atherosclerotic syndrome by reducing obesity, significantly inhibiting VCAM-1, MCP-1, TNF-α, and IL-1β expression, and increasing the production of SCFAs." (PMID 35256637, 2022). "IL-1β antibody treatment improves insulin resistance, glycemic control, and β-cell functions in mice with HFD-induced obesity." (PMID 36230963, 2022). "Inflammatory cytokines in adipose tissue induced by obesity, such as TNF-α, IL-1β, and IL-6, increased." (PMID 35883829, 2022). "Accumulating evidence indicates that adipose tissue of obese subjects has higher NLRP3 compartments and IL-1β expression compared to that of lean individuals, showing positive correlation between NLRP3 signaling in adipose tissue and obesity." (PMID 36142842, 2022). "Microglial cells are one of the major immune cells releasing IL-1β, TNF-α and IFN-γ which plays a critical role in brain inflammation in high-fat diet induced obesity." (PMID 35154484, 2022). "We previously showed that diet-induced obesity in mice increased AHR in association with increased IL-1β gene expression in the lung and IL-1β receptor blockade by anakinra prevented obesity-induced AHR, suggesting a mechanistic role of IL-1β in obese asthma." (PMID 35574481, 2022). "Circulating IL-1Ra is increased in obesity and T2DM and correlates with insulin resistance, while intracellular β-cell-derived IL-1Ra is downregulated in T2DM leading to IL-1β-induced β-cell dysfunction and apoptosis." (PMID 34990893, 2022). "In our study, the results of ELISA illustrated the effects of exercise on TNF-α, IL-1β, and IL-10 levels in the serum of mice with HFD-induced obesity." (PMID 36145106, 2022). "The results showed that CIP decreased the serum levels of inflammatory cytokine TNF-α and the mRNA expression levels of IL-6, IL-1β, and TNF-α in mice, suggesting that CIP improved inflammation during the development of obesity." (PMID 36235584, 2022). "Studies have shown increased expression of inflammatory markers (i.e., TNF-α, IL-1β, and IL-6) by adipose tissue in mice with HFD-induced obesity." (PMID 35456900, 2022). "Activated C-Jun transcription factors bind to AP-1 sites, thereby promoting the expression of pro-inflammatory factors (e.g., TNFα, IL1β, IL6, etc.), which play a key role in impaired glucose tolerance and insulin resistance by HFD-induced obesity." (PMID 35715850, 2022). "By the correlation analysis, we identified 35 key genera, which were significantly correlated with features of obesity (body weight gain), dyslipidemia (TC, TG, HDL‐C, and LDL‐C), proinflammatory cytokines (serum IL‐6, IL‐1β, and TNF‐α), and LPS." (PMID 36348812, 2022). "We found that plasma IL-1β, IL-6, IL-8, IL-12, IL-17, IL-21, IL-32, and TNF-α levels were elevated in obese children with NAFLD compared to subjects with simple obesity." (PMID 36530698, 2022). "A PTSD transcriptomic study evaluating the effects of Body Mass Index (BMI) and sex found that IL-1B is differentially expressed in PTSD males with high BMI, implicating IL-1B in the comorbidity of obesity and metabolic syndromes in PTSD." (PMID 35625844, 2022). "HFD-induced obesity resulted in the increased secretion of several inflammatory cytokines such as TNF-α and IL-1β." (PMID 34960036, 2021).
Obesity (continued). "Obesity is accompanied by chronic inflammation due to an increased production of pro-inflammatory cytokines like TNF-α and IL-1β, which are activated by NF-κB." (PMID 32882776, 2021). "Amongst the factors that exhibited statistically significant differences between the lean and obese groups with obesity at T3 were myeloid factors, including CCL4, IL-1β, IL-1RA, and IL-27." (PMID 34195568, 2021). "Previous reports indicated that MAPK1 contributes to the elevated secretion of monocyte chemoattractant protein-1 (MCP-1), and MAPK3 is associated with enhanced mRNA levels of inflammatory markers, such as CCL2, IL1β, and TNF-α in obesity." (PMID 34360840, 2021). "As far as we know, our investigation is the first investigation that has examined the relationship between LCD and sleep quality mediated by inflammatory factors (hs‐CRP, TAC, IL‐1β, TGF‐β) in the problem of overweight and obesity among women." (PMID 34760255, 2021). "Here, we demonstrate that microglial necroptosis plays a pivotal role in obesity-related hypothalamic inflammation, facilitating proinflammatory cytokine production, such as TNF-α and IL-1β." (PMID 34750365, 2021). "Other labs have also investigated the involvement of IL-1β and the NLRP3 inflammasome in the propagation of myelopoiesis in obesity." (PMID 33554957, 2021). "PVA and alginate nanofibers can modulate obesity, reduce blood glucose levels, and reduce serum levels of insulin, ALT, ALP, GGT, creatinine, TNF-α, and IL-1β in diabetic rats." (PMID 34083930, 2021). "In conclusion, NLRP3 inflammasomes are critical for the development and progression of obesity and T2DM, especially IL-1β, a product of NLRP3 inflammasome activation." (PMID 34737754, 2021). "We propose that in skeletal muscle, obesity activates the NLRP3 inflammasome, which in turn cleaves and activates IL-1β." (PMID 34638553, 2021). "Consistent with our study, type 2 diabetes mellitus, obesity, and insulin resistance result in persistent production of proinflammatory cytokines such as TNF-α, IL-1β, and IL-6, which typically inhibit adipogenesis." (PMID 34051860, 2021). "Our results showed higher plasma levels of IL-6, IL-1β, TNF-α, IL-8, IL-12, and IL-18 in subjects with obesity before bariatric surgery when compared with the postoperative state." (PMID 34108550, 2021). "An increase in circulating levels of cytokines (IL-1β, IL-6, and IL-17A) and their production under the influence of the HFCD diet is also specific for the development of diet-induced obesity and metabolic syndrome." (PMID 33670919, 2021). "Chronic inflammation mediated by HFHSD-induced obesity is marked by increased pro-inflammatory cytokines such as TNF-α, IL-1β, and IL-6 in circulation." (PMID 32143330, 2020). "We assessed the levels of the cytokines IL-1β, IL-6, and TNF-α as well as the chemokine RANTES since previous studies have shown that they are elevated in liver of diet-induced rodent models of obesity and contribute to NAFLD pathogenesis." (PMID 32751772, 2020). "Molecular markers of obesity (e.g. IL-6, CRP, leptin, interleukin 1 beta [IL-1β]) increase the generation of myeloid-derived suppressor cells (MDSCs)." (PMID 33123173, 2020). "We conclude that pathways that process pro-IL-1β to bioactive IL-1β play an important role in promoting the development of NAFLD and obesity-induced inflammation." (PMID 32002713, 2020). "The production of inflammatory mediators, including monocyte chemoattractant protein-1 (MCP-1), interleukin (IL)-6, IL-1β, and tumor necrosis factor (TNF)α, increases with obesity since macrophages contribute to the production of them." (PMID 32019160, 2020). "In obesity, activated WAT and the resident macrophages secrete inflammatory cytokines, such as TNF-α, IL-6, and IL-1β into the bloodstream, which stimulates hepatocytes and Kupffer cells." (PMID 33187321, 2020).
Obesity (continued). "In obesity, adipose tissue exhibited the lower activities of antioxidant enzymes (CAT, SOD, and GSH-Px) and the higher levels of cytokines (TNF-α, IL-1β, and IL-6) and ROS generation." (PMID 32104715, 2020). "Particularly, we confirmed that the extent of upregulation of three genes including IL-6, IL-1β, and TNF-α, i.e., the three most studied inflammatory genes related to obesity, was significantly greater in ‘Lean_Ag-DEGs’ than in ‘Obese_Ag-DEGs’ (P < 0.01)." (PMID 33183332, 2020). "Therefore these studies suggest that anti IL-1β therapy may prevent the metastatic cascade if given early in the disease process, and further studies are required to examine if metastatic spread is also prevented in people living with obesity." (PMID 33339340, 2020). "IL-1β and MCP-1 expression in obesity appears to be vital for phenotypic and functional M1 polarization of monocytes/macrophages in response to TNF-α24." (PMID 33033337, 2020). "In our study, increased levels of resistin, TNF-α, IL-1β, and IL-6 were observed in the spleen in DIO mice, which suggested that the changes of cytokine in the spleen in obesity were indicative of altered immune functions." (PMID 32104715, 2020). "Further, corroborating the literature, we observed that obesity increased serum levels of proinflammatory cytokines TNF-α and IL-1β, and this improvement on inflammatory profile culminated in a lower hepatic sensitivity to insulin." (PMID 32847099, 2020). "In the present study, the obesity condition increased serum TNF-α and IL-1β, and the exercise protocol was sufficient to revert this parameter." (PMID 32847099, 2020). "In response to calorie restriction and exercise, gene expressions of IL-1β and NLRP3 are reduced in the subcutaneous fat of patients with obesity and type 2 diabetes, accompanied with improvement in insulin sensitivity." (PMID 32545355, 2020). "Decreased production of NRG4 in obesity is likely due to direct impact of pro-inflammatory cytokines produced in obesity such as TNF-α and IL-1β." (PMID 32175323, 2020). "Studies have also indicated that inflammatory cytokines such as IL-1β, TNF-α, and IL-6 which are increased in obesity and diabetes conditions modulate insulin signaling." (PMID 33293987, 2020). "SLKDT intervention significantly inhibited obesity‐induced inflammation by decreasing the proinflammatory factors IL‐6, TNF‐α, IFN‐γ, and IL‐1β and increasing the anti‐inflammatory cytokines IL‐4 and IL‐10." (PMID 32884731, 2020). "M1 pro‐inflammatory macrophages induced the secretion of IL‐1β, IL‐6, IL‐12, TNF‐α, CCL5 and CCL2 in adipose tissue during obesity." (PMID 32458441, 2020). "This was manifested by a reduction in both the expression and the release of proinflammatory cytokines, which are key in the development of obesity-related complications, such as TNF-α, IL-1β, and IL-6." (PMID 31438646, 2019). "In most rodent studies, anakinra (antagonizes both IL-1β and IL-1α), specific anti-IL-1β antibodies, or TNF-α blockers were applied in a preventive fashion in diet-induced mouse obesity models or in the GK rat." (PMID 30989320, 2019). "In adipose tissues in obesity, expressions of pro-inflammatory cytokines such as MCP-1, IL-6, TNFα, and IL-1β in macrophages and/or adipocytes have been reported to increase." (PMID 31509948, 2019). "In conclusion, TNF-α, IL-6 and IL-1β are increased in psoriasis and correlate with PASI scores and obesity, leading to worsening of psoriatic lesions." (PMID 31521168, 2019). "As in adipose tissue, macrophages infiltrate and accumulate in pancreatic islets of obese T2DM individuals and diet-induced obesity mice, which produce proinflammatory cytokines and chemokines, such as TNF-α, IL-1β, and MCP1." (PMID 31582899, 2019). "In the obese state, necrotic adipocyte recruits macrophages to secret pro-inflammatory cytokines, such as TNF-α, IL-1β, IL-6, MCP-1, which potentially arouses obesity-related insulin resistance." (PMID 31548850, 2019).